GABRB2 (gamma-aminobutyric acid type A receptor subunit beta2)
Description:
Beta subunit of the heteropentameric ligand-gated chloride channel gated by gamma-aminobutyric acid (GABA), a major inhibitory neurotransmitter in the brain. GABA-gated chloride channels, also named GABA(A) receptors (GABAAR), consist of five subunits arranged around a central pore and contain GABA active binding site(s) located at the alpha and beta subunit interface(s). When activated by GABA, GABAARs selectively allow the flow of chloride anions across the cell membrane down their electrochemical gradient (By similarity). Chloride influx into the postsynaptic neuron following GABAAR opening decreases the neuron ability to generate a new action potential, thereby reducing nerve transmission (By similarity). GABAARs containing alpha-1 and beta-2 or -3 subunits exhibit synaptogenic activity; the gamma-2 subunit being necessary but not sufficient to induce rapid synaptic contacts formation. Extrasynaptic beta-2 receptors contribute to the tonic GABAergic inhibition (By similarity). Beta-containing GABAARs can simultaneously bind GABA and histamine where histamine binds at the interface of two neighboring beta subunits, which may be involved in the regulation of sleep and wakefulness (By similarity).
Synonyms: DEE92; ICEE2
Tractability: Small molecule: an approved drug acts on it; a structure with a bound ligand is known; a high-quality ligand is known; it belongs to a druggable protein family. Antibody: UniProt places it where antibodies can reach, with high confidence; its Gene Ontology location is reachable by antibodies, with high confidence; UniProt predicts a signal peptide or a membrane-spanning region. PROTAC: ubiquitination databases record sites on it; its protein half-life has been measured; a small molecule that binds it is known.
Target class: Ion channel; GABA-A receptor; Ligand-gated ion channel
Gene: Protein-coding gene on chromosome 5 (161,288,429 to 161,549,044, reverse strand). Ensembl gene ENSG00000145864.
Subcellular location: Postsynaptic cell membrane; Cell membrane; Cytoplasmic vesicle membrane
Pathways (Reactome):
Neuronal System: GABA receptor activation
Signal Transduction: Signaling by ERBB4
Gene Ontology:
Molecular function: GABA receptor activity; GABA-gated chloride ion channel activity; chloride channel activity; GABA-A receptor activity; extracellular ligand-gated monoatomic ion channel activity; monoatomic ion channel activity; transmembrane signaling receptor activity; transmitter-gated monoatomic ion channel activity involved in regulation of postsynaptic membrane potential
Biological process: chloride transmembrane transport; gamma-aminobutyric acid signaling pathway; inhibitory synapse assembly; cellular response to histamine; chemical synaptic transmission; extrasynaptic signaling via GABA; negative regulation of synaptic transmission, GABAergic; synaptic transmission, GABAergic; cochlea development; inner ear receptor cell development; innervation; monoatomic ion transmembrane transport; monoatomic ion transport; neuron development; regulation of postsynaptic membrane potential
Cellular component: dendritic spine; extracellular exosome; GABA-A receptor complex; plasma membrane; postsynaptic membrane; cytoplasmic vesicle membrane; GABA-ergic synapse; postsynaptic specialization membrane; membrane
Genetic constraint (gnomAD): Loss-of-function variants: 13 observed, 48.47 expected, observed/expected ratio (o/e) 0.27, 90% interval 0.17 to 0.43. The upper end of that interval is the gene's LOEUF score, 0.43, which puts it in group 1 of 6, group 1 being the genes least tolerant of losing a copy. Missense variants: 346 observed, 627.03 expected, observed/expected ratio (o/e) 0.55, 90% interval 0.5 to 0.6. Synonymous variants: 231 observed, 230.26 expected, observed/expected ratio (o/e) 1, 90% interval 0.9 to 1.12.
Gene-disease validity (ClinGen):
ClinGen rates the evidence that GABRB2 causes each of these diseases.
complex neurodevelopmental disorder (autosomal dominant): Definitive. A disorder that involves more than one phenotype associated with the central nervous system, including but not limited to intellectual disability, autism, and seizures (epilepsy).
Homologues: Orthologues: chimpanzee GABRB2 (100% identical), macaque GABRB2 (100% identical), guinea pig GABRB2 (99% identical), rabbit GABRB2 (99% identical), rat Gabrb2 (97% identical), pig GABRB2 (97% identical), mouse Gabrb2 (92% identical), dog GABRB2 (89% identical), tropical clawed frog gabrb2 (87% identical), zebrafish GABRB2 (78% identical), zebrafish gabrb2a (68% identical). Paralogues in human: GABRB1 (73% identical), GABRB3 (72% identical), GABRQ (39% identical), GABRR1 (34% identical), GABRR2 (34% identical), GABRD (34% identical), GABRP (33% identical), GABRG2 (33% identical), GABRR3 (33% identical), GLRA2 (33% identical), GLRA1 (32% identical), GLRA3 (32% identical), and 33 more.
Diseases named in the same sentence as GABRB2 in open-access papers:
GABRB2 is named in the same sentence as 69 diseases in open-access papers, as found by Europe PMC text mining. Sharing a sentence is not in itself a finding about the gene and the disease. The quoted sentences say what the papers report.
schizophrenia (23 papers, 2007 to 2025). A major psychotic disorder characterized by abnormalities in the perception or expression of reality. "Yet, our results cooperate with another study on Han Chinese, which also rejects GABRB2 as a susceptibility gene for schizophrenia." (PMID 40977746, 2025). "The results contradict the proposition that GABRB2 is a susceptibility gene for schizophrenia, at least in our studied population." (PMID 40977746, 2025). "Several intronic SNPs in GABRB2, particularly in the non-coding regions targeting exon 10 (a key site for alternative splicing), have been strongly associated with schizophrenia." (PMID 40977746, 2025). "In conclusion, this study explored the association of the ERBB4 rs839523C/T and GABRB2 rs1816072 T/C polymorphisms with schizophrenia risk in the Lebanese population." (PMID 40977746, 2025). "One of such cases has been well evident in a 3551-bp segment of the schizophrenia-associated GABRB2 gene that codes for the β2 subunit of GABAA receptor." (PMID 33741065, 2021). "For GABRB2 as well strong evidence exists to be a causative gene for schizophrenia and it seems to be involved in opioid addiction." (PMID 33004014, 2020). "Intronic polymorphisms of the GABAA receptor β2 subunit gene (GABRB2) under adaptive evolution were associated with schizophrenia and reduced expression, especially of the long isoform which differs in electrophysiological properties from the short isoform." (PMID 30013074, 2018). "Previously, analysis of schizophrenia genomics pointed to GABRB2 as a key susceptibility gene for schizophrenia." (PMID 30013074, 2018). "In case-control studies, significant association of GABRB2 has been observed with various psychotic disorders including autism, bipolar disorder, epilepsy, schizophrenia, and alcohol dependence." (PMID 26561861, 2015). "The occurrence of positive selection in schizophrenia-associated GABRB2 suggests a broader impact of the gene product on population fitness." (PMID 23638040, 2013). "This GABRB2-schizophrenia association has since been validated by independent studies on multiple ethnic groups." (PMID 20221451, 2010). "The schizophrenia-associated S1–S29 segment (3,551 bp) of GABRB2 contains a human specific Alu-Yi6 element, and SNPs that were found to be subject to positive selection." (PMID 20221451, 2010). "Within the schizophrenia-associated 3,551-bp region of human GABRB2, the human lineage displayed accelerated evolutionary adaptation." (PMID 17520021, 2007). "Among the genes implicated in schizophrenia are gamma-aminobutyric acid A receptor beta 2 (GABRB2) and Erb-B2 Receptor Tyrosine Kinase 4 (ERBB4), which encode the Gamma-Aminobutyric Acid Type A Receptor Beta2 Subunit and the Erb-B2 Receptor Tyrosine Kinase 4, respectively." (PMID 40977746, 2025). "As for GABRB2, it has been implicated with schizophrenia in previous studies." (PMID 40977746, 2025). "Therefore, the present study aims to investigate the potential association between the ERBB4 rs839523C/T and GABRB2 rs1816072 T/C polymorphisms, alongside selected environmental factors, in contributing to schizophrenia risk within the Lebanese population." (PMID 40977746, 2025). "Interestingly, the behaviors observed in our Gabrb3ECKO mice were most similar to the constitutive Gabrb2 knockout mice, a model that has been linked to schizophrenia." (PMID 35318369, 2022). "Furthermore, in previous studies, we identified putative enhancer RNAs that target schizophrenia-associated genes as well as numerous genetic variants in genes that have been previously linked to schizophrenia, namely GABRB2, SPATS2L, ZEB2, and KCHN8." (PMID 34954808, 2022). "Considering the uniqueness of human recombination hotspots and positive selection of the alleles in GABRB2, gene conversion within the intronic S1-S29 segment could be a potential cause leading to the pathogenesis of schizophrenia and heroin dependence." (PMID 26561861, 2015).
schizophrenia (continued). "Subsequently the suggestion was also made that positive selections might have acted as well on other schizophrenia-associated genes besides GABRB2." (PMID 20221451, 2010). "More recently, schizophrenia-association was established for GABRB2 located at chromosome 5q34, and its genotypes have been correlated to splicing variations of β2-subunit isoforms that give rise to different electrophysiological consequences in type A γ-amino-butyric acid (GABAA) receptor function." (PMID 20221451, 2010). "Additionally, genetic and epigenetic analyses have identified glial dysregulation in schizophrenia risk, including variants (e.g., gamma-aminobutyric acid A receptor beta 2—GABRB2) and demonstrated disruption of astrocyte–microglia crosstalk in KO mouse models." (PMID 40427508, 2025). "As well, the association between GABRB2 and schizophrenia has been validated by multiple genetic studies on different ethnic populations, and SNPs, haplotypes and CNVs in the 3551-bp segment are found to be associated with schizophrenia taking a candidate gene approach." (PMID 33741065, 2021). "The evolutionary history of the region surrounding Yi6AH151 could be reconstructed from the male genotype frequencies from the AF and the three non-AF populations together with the Chinese cohort (CH) employed in the initial report on GABRB2-schizophrenia association." (PMID 17520021, 2007). "The DKO exhibits a similar phenotype of sociability impairment of Gabrb2 KO mice but with some differences, such as a schizophrenia-like phenotype, particularly increased body weight and food intake." (PMID 39875098, 2025). "GABRB2 is an ionotropic type A γ-aminobutyric acid (GABA) receptor, which has been linked to schizophrenia in multiple studies." (PMID 34954808, 2022). "A wide range of schizophrenia-like phenotypes displayed by the GABRB2-knockout mice, and the reversal of these phenotypic alterations by antipsychotic drug further underline the pivotal role of GABRB2 in the development of schizophrenia." (PMID 33741065, 2021). "Some researchers believe that GABRB2 is related to schizophrenia, but this view is widely controversial." (PMID 33506048, 2021). "The decreased depression-like behavior in the tail-suspension and sucrose-preference tests, and anxiety-like behavior in the elevated-plus maze in Gabrb2-knockout mice, indicated a separation of the schizophrenia type symptoms from comorbid affective symptoms." (PMID 30013074, 2018). "The present study was directed to examining the gene dosage effects of Gabrb2 in knockout mice of both heterozygous (HT) and homozygous (KO) genotypes with respect to possible schizophrenia-like and comorbid phenotypes." (PMID 30013074, 2018). "(c) Gabrb2 knockout in mice produced a range of schizophrenia-like symptoms and comorbidities, some of which are reversed partly or fully by the antipsychotic risperidone." (PMID 30013074, 2018). "These extensive schizophrenia-like and comorbid phenotypes brought about by Gabrb2 knockout, in conjunction with our previous findings on GABRB2 association with schizophrenia, support a pivotal role of GABRB2 in schizophrenia etiology." (PMID 30013074, 2018). "In the present study, Gabrb2-knockout mice of both homozygous (KO or Gabrb2−/−) and heterozygous (HT or Gabrb2+/−) genotypes were compared to wild-type (WT or Gabrb2+/+) mice regarding the possible presence of schizophrenia-like phenotypes." (PMID 30013074, 2018). "Meta-analytic results of SNPs in GABRB2 and schizophrenia in different ethnic subgroups combined with GWAS data." (PMID 29894498, 2018). "Earlier findings on schizophrenia genomics, gene expression and alternate-splicing of the β2 receptor subunit have pointed to a key role played by GABRB2 genotypes and haplotypes in the disease." (PMID 30013074, 2018). "Accordingly, the present study suggested the shared genetic basis of GABRB2 in schizophrenia and heroin dependence." (PMID 26561861, 2015).
schizophrenia (continued). "The present study provide evidence for the schizophrenia candidate gene GABRB2 to play a role in heroin dependence, but replication of these findings is required." (PMID 26561861, 2015). "GABRB2, a schizophrenia candidate gene coding for GABAA receptor β2 subunit, is examined for possible association with heroin dependence in Han Chinese population." (PMID 26561861, 2015). "The co-occurrence of hotspot recombination and positive selection in the S1–S29 segment of GABRB2 has provided a plausible contribution to the molecular genetics mechanisms for schizophrenia." (PMID 20221451, 2010). "Non-coding single nucleotide polymorphisms (SNPs) in GABRB2, the gene for β2-subunit of gamma-aminobutyric acid type A (GABAA) receptor, have been associated with schizophrenia (SCZ) and quantitatively correlated to mRNA expression and alternative splicing." (PMID 19763268, 2009). "Intronic SNPs and haplotypes in GABRB2, the gene for GABAA receptor β2 subunit, are associated with schizophrenia and correlated with the expression of two alternatively spliced β2 isoforms." (PMID 17520021, 2007). "For instance, a Dicer1 dependent disruption of miRNA biogenesis and the lack of GABRB2 expression have been linked to schizophrenia pathogenesis." (PMID 34954808, 2022). "The results obtained provided evidence for a GABRB2-origin of schizophrenia." (PMID 30013074, 2018). "Multiple evidences showed that GRIA1 and GABRB2 are relevant to Bipolar Disorder and Schizophrenia." (PMID 24901472, 2014). "Since the β2L and β2S expressions are associated with SCZ, and also produce different effects on GABAA receptor run-downs, they could provide a fundamental link between GABRB2 genotypes and physiological perturbations in schizophrenia." (PMID 19763268, 2009). "As in the case of most other genes underlying complex disorders, the schizophrenia-associated DNA sequence polymorphisms in GABRB2 are located in the non-coding regions, and therefore not immediately evident in their functional implications." (PMID 17520021, 2007). "Although single-nucleotide polymorphisms in GABRB2, the gene encoding for GABAA receptors β2 subunit, have been associated with schizophrenia (SCZ), it is unknown whether there is any association of copy number variations (CNVs) in this gene with either SCZ or premenstrual dysphoric disorder (PMDD)." (PMID 32695026, 2020). "An inhibition demand hypothesis may be proposed to address the biological basis of the overall positive selection of derived genotypes in GABRB2, and its potential significance to the etiology of schizophrenia and possibly also other psychiatric disorders involving GABAA." (PMID 17520021, 2007). "Other disorders found to involve MCP-related genes include schizophrenia (FOXP2 and GABRB2), intellectual disability and epilepsy (GABRB2), and neuroleptic-induced tardive dyskinesia (GABRB2)." (PMID 31194737, 2019). "Furthermore, it was recently shown in a murine knockout model that the lack of GABRB2 leads to various schizophrenia-like symptoms, which goes in line with our observations." (PMID 34954808, 2022). "Furthermore, the dissimilarities between the symptoms of schizophrenia and those observed so far in the Gabra1 and Gabra5 knockouts suggest that the extensive similarities between Gabrb2 knockout and schizophrenia are not readily shared by knockouts of other subunits of GABAA receptors." (PMID 30013074, 2018).